USP28 (ubiquitin specific peptidase 28)
Diseases named in the same sentence as USP28 in open-access papers (continued):
Sharing a sentence is not in itself a finding about the gene and the disease.
tumor (continued). "In this review, we summarize the correlation between USP28 and tumor behaviors, aiming to provide guidance for future experimental designs and emphasize the potential of targeting USP28 for cancer therapy." (PMID 36879346, 2023). "USP28 can induce tumor angiogenesis directly and indirectly through the deubiquitination of HIF-1α and c-Myc." (PMID 36879346, 2023). "The study found that the stabilization of ZNF304 by USP28 results in the hypermethylation and transcriptional silencing of tumor-suppressor genes during oncogenic transformation, consistent with the results of the physical interactions." (PMID 37450415, 2023). "In keeping with the increased USP28 protein, qRT-PCR data indicated that the mRNA expression level of USP28 in tumor tissues was higher than in adjacent tissues." (PMID 37450415, 2023). "The tumor-promoting role of USP28 and relevant investigations are currently dominant; nevertheless, several studies have demonstrated its oncostatic effects." (PMID 36879346, 2023). "Genetic deletion of Usp28, which has previously been shown to lower ΔNp63 and reduce tumour formation in mouse SCC, from these tumours (KPLU) also dramatically decreased levels of nuclear Srebp2." (PMID 37202505, 2023). "USP28 has been described to have both tumor-suppressive and oncogenic roles, depending on the cellular context." (PMID 35326457, 2022). "Already in low‐grade primary tumours, Usp28 and its substrates were significantly upregulated when compared to adjacent, nontransformed lung epithelial tissue." (PMID 35364627, 2022). "The increase in Usp28 and the oncogenic transcription factors persisted in higher grade tumours, as seen by IHC, thereby confirming the observation made in patients." (PMID 35364627, 2022). "Tumour cells are addicted to USP28 to allow oncogenic transformation, and its inhibition via the small‐molecule inhibitor AZ1 partially reverts the oncogenic transformation." (PMID 35364627, 2022). "In KPLU tumors, the overall protein abundance of the FA proteins FANCD2 and FANCI were significantly reduced compared to USP28-proficient tumor samples, demonstrating that the USP28-∆Np63 axis maintains FA expression in vivo." (PMID 34611298, 2022). "To assess the role of USP28 activity on the FA pathway in vivo, we used a CRISPR/Cas9 expressing mouse strain, in combination with AAV virions, for tumor induction and depletion of USP28 in the lung." (PMID 34611298, 2022). "Immuno-histochemical analysis of tumor-bearing lungs from murine SCC transplant animals revealed that in control treated animals USP28 and its substrate ∆Np63 were detectable, along with the ∆Np63 target FANCD2." (PMID 34611298, 2022). "Consistently, a first-generation small molecule inhibitor of USP28 (AZ1) suppressed tumor growth in a murine isogenic transplant model." (PMID 34611298, 2022). "Targeting USP28, by shRNA depletion or pharmacological inhibition, resulted in a reduced tumor burden in an in vivo lung tumour model." (PMID 34611298, 2022). "The combination of USP28 inhibition and cisplatin further induced DNA damage, leading to tumor shrinkage, while wild type tissue tolerated the treatment." (PMID 34611298, 2022). "Western blot analysis of primary tumor material comparing KPL and KPLU showed the expected depletion of USP28 and loss of ∆Np63." (PMID 34611298, 2022).
tumor (continued). "Overall, our data demonstrated that USP28 is required to maintain tumour cell proliferation and survival in cellulo; hence, tumour cells become addicted to USP28." (PMID 35364627, 2022). "Because of its deubiquitinase activity, USP28 interacts with Myc to catalyse the deubiquitination of Myc, thereby promoting its stabilisation and contributing to tumour cell growth in colon and breast carcinomas." (PMID 34584067, 2021). "USP28 is a deubiquitylase that is extensively characterized in several tumor entities, such as colorectal cancer." (PMID 34685632, 2021). "Ubiquitin-specific protease 28 (USP28), a member of the DUBs family, functions as a potential tumour promoter in various cancers." (PMID 34584067, 2021). "Mice bearing USP28-silenced cells showed a notable decrease in tumour weight and volume; whereas, simultaneous overexpression of FOXM1 fully abolished the anti-tumour effect of USP28-knockdown." (PMID 34584067, 2021). "Here, we showed that PC tumours had higher USP28 expression compared with that of normal pancreatic tissues, and high USP28 level was significantly correlated with malignant phenotype and shorter survival in patients with PC." (PMID 34584067, 2021). "Lastly, USP28 also acts as a tumor suppressor, inducing H2A-mediated transcriptional activation of tumor-suppressor genes." (PMID 34685632, 2021). "Previous studies have shown that USP28 also acts as an oncoprotein in different tumor entities, such as glioblastoma and breast cancer." (PMID 34685632, 2021). "The frequent overexpression of USP28 in PC tumours and cell lines prompted us to explore its oncogenic role in PC." (PMID 34584067, 2021). "As USP28 was detectable by immunohistochemistry in all tumours, we assessed the effect of AZ1 on USP28 activity." (PMID 32128997, 2020). "Concomitant targeting of USP28 at the time of tumour induction significantly affected NSCLC formation." (PMID 32128997, 2020). "The observed effects of USP28 depletion during tumour induction suggest that USP28 is required for SCC formation in vivo." (PMID 32128997, 2020). "Tumours developing in KPL mice showed expression of USP28 and ∆Np63, while USP28 was strongly reduced in isolated tumours from KPLU mice and ∆Np63 was not detectable." (PMID 32128997, 2020). "Our data strongly suggest that targeting ∆Np63 abundance via inhibition of USP28 is a promising strategy for the treatment of SCC tumours." (PMID 32128997, 2020). "Next, we determined the abundance of USP28 protein via immunohistochemistry (IHC) on tissue microarrays and tumour sections of a total of 300 human lung tumour samples." (PMID 32128997, 2020). "To test the role of USP28 in tumour induction, we included two sgRNA cassettes targeting USP28 into the experimental cohort of KPL mice (USP28∆, referred to as KPLU)." (PMID 32128997, 2020). "Evaluation of USP28 abundance, estimated by IHC, demonstrated an increase in USP28 protein in SCC tumours compared to ADC tumours within the same KPL animal." (PMID 32128997, 2020). "In non‐treated mice, active USP28 was detectable in in vivo tumour samples, however, treatment of mice with AZ1 blocked USP28 activity, and resulted in a marked reduction in USP28 protein abundance (Fig EV5C)." (PMID 32128997, 2020).
tumor (continued). "We found that USP28 is frequently upregulated in human SCC tumours and is often co‐expressed with ∆Np63." (PMID 32128997, 2020). "In strong support of this notion, targeting USP28 in a model of lung SCC (“KPL mice”) using the CRISPR/Cas9 system reduced the total number of tumours and, specifically, abrogated the formation of the SCC subtype." (PMID 32128997, 2020). "Stratification of patients into two groups based on the expression of USP28 determined that patients with low expression of USP28 had significantly reduced survival and reduced tumor-free survival." (PMID 29880484, 2018). "Silencing of USP28 expression in A373-C6 xenografts significantly decreased sensitivity to vemurafenib-induced tumor shrinkage at both concentrations tested, compared with control mice." (PMID 29880484, 2018). "The protein FBXW7-185aa functions as a tumor suppressor by competitively binding with USP28, and preventing USP28 binding to FBXW7α, subsequently inhibiting USP28-induced c-myc stabilization." (PMID 30111313, 2018). "USP28 was the first FBW7-antagonizing DUB in an shRNA screen using c-MYC stability as a readout in human tumor cells." (PMID 29415985, 2018). "Our data suggested that USP28 was a tumour-promoting factor and a promising therapeutic target for NSCLC." (PMID 25656529, 2015). "Notably, combining a USP28 inhibitor with anti-PD-1 immunotherapy results in enhanced tumor regression and significantly prolonged overall survival in mouse tumor models." (PMID 42189121, 2026). "Finally, loss of USP28 destabilized MAST1 protein and attenuated tumor growth by sensitizing cells to cisplatin treatment in mouse xenograft model." (PMID 38498222, 2024). "However, mice bearing USP28-depleted cells reconstituted with USP28 or MAST1 displayed increased tumor size, volume and weight." (PMID 38498222, 2024). "Compared to wildtype USP28, monomeric USP28 had a stronger stabilizing effect on MYC in HLF cells and in a p19Arf-deficient, Nras-transformed murine HCC cell line established from an autochthonous tumor (p19-/-Nras)." (PMID 38227944, 2024). "USP28 was proposed to act as both an oncogene and a tumor suppressor." (PMID 39398482, 2024). "Furthermore, we showed that the loss of USP28 downregulates MAST1 protein level and sensitizes cells for cisplatin toxicity during tumor growth, leading to reduced tumor size, volume and weight." (PMID 38498222, 2024). "Additionally, based on the HPA website, immunofluorescence images revealed that the USP28 protein was predominantly localized and distributed in the nucleus of U251-MG, U2-OS, and A431 tumor cell lines." (PMID 37450415, 2023). "Furthermore, pharmacologic inhibition of USP28 negatively affected LSCC tumour growth and was well tolerated in vivo." (PMID 37202505, 2023). "Interestingly, the mechanistic action of this circRNA was identified as a “molecular sponge” of miR-633-3p, an miRNA molecule that negatively regulates USP28 (ubiquitin-specific peptidase 28) expression, therefore functioning as a tumor suppressor." (PMID 37373059, 2023). "Finally, the functional experiments confirmed that USP28 significantly promoted proliferation, invasion, and migration, which agrees with previous tumor studies." (PMID 37450415, 2023). "Our findings suggest that USP28 targets SREBP2 to drive LSCC tumour growth." (PMID 37202505, 2023). "Moreover, DUBs like USP22 play a role in promoting tumor development through the regulation of epigenetic changes, while others such as USP28 and USP7 are involved in controlling the turnover of oncogenes or tumor suppressors." (PMID 37626927, 2023). "In this review, we summarize the correlation between USP28 and tumor behaviors." (PMID 36879346, 2023).
tumor (continued). "Let-7 is a tumor suppressor that also plays an essential role in the acceleration of cell differentiation; hence, we infer that USP28 may inhibit cell differentiation through its indirect function on let-7." (PMID 36879346, 2023). "USP28 plays an indispensable role in tumor progression by regulating multiple signaling pathways." (PMID 37450415, 2023). "Tumours from KPL mice also displayed a high percentage of nuclei that were positive for Usp28." (PMID 37202505, 2023). "Moreover, mutations in MMR genes can disrupt the stability and integrity of the entire genome in normal cells, which also shows that USP28 plays a vital part in tumor growth and spread." (PMID 37450415, 2023). "Therefore, understanding the molecular mechanisms by which USP28 supports tumour formation is vital for the rational targeting of LSCC." (PMID 37202505, 2023). "Moreover, acute deletion of Usp28 using a dual recombinase model resulted in regression of tumours formed by induction of mutant KrasG12D in combination with Fbw7 deletion." (PMID 37202505, 2023). "Thus, although USP28 contributes to cell cycle arrest here, it actually functions in tumor promotion and contributes to the drug resistance." (PMID 36879346, 2023). "The results have pinpointed the potent roles of USP28 across tumor types, especially in HCC." (PMID 37450415, 2023). "In addition, in wild-type C57BL/6J mice transplanted with murine lung tumor cells, compared with the control mice, AZ1 reduced the tumor burden in a dose-dependent manner and blocked the activation and reduced the abundance of USP28." (PMID 36879346, 2023). "Next, we were intrigued if USP28 expression is altered relative to tumour type and/or grade." (PMID 35364627, 2022). "Analysing survival data and correlating USP28 expression to tumour stages, it became clear that, especially at early stages, USP28high expressing tumours significantly correlated with an overall shortened survival, and this observation was independent of tumour subtype." (PMID 35364627, 2022). "In lung, and as previously reported for SCC, targeting USP28 presents a suitable lever for therapeutic engagement, as one could propose that at least in lung, tumour cells become addicted to USP28." (PMID 35364627, 2022). "Since NSCLC is a genetically very heterogeneous tumour type, next, we wondered whether patient survival depended on the combination of oncogenic driver and the expression of USP28." (PMID 35364627, 2022). "Finally, we performed in vivo tumorigenesis assays to confirm the relevance of this signaling axis in tumors and further investigate the role of USP28 in tumor growth." (PMID 35326457, 2022). "Analysis of publicly available data regarding putative drug sensitivity of tumour cells in direct correlation to USP28 expression scored the PIK3, EGFR and MAPK pathway as top hits, which directly confirmed our experimental data regarding USP28 expression relative to oncogenic drivers." (PMID 35364627, 2022). "Similarly, tumour tissue explants revealed a significant reduction in USP28 and FANCD2 upon treatment with AZ1." (PMID 34611298, 2022). "Furthermore, USP28-overexpression PC cells resulted in significantly greater tumour growth and tumour weight, when compared to their respective controls." (PMID 34584067, 2021). "Considering the strong functional interconnection between DUB USP28 and E3-ligase FBXW7, the genetic status of FBXW7 may be important to clarify the role of USP28 as an oncoprotein or tumor suppressor." (PMID 34685632, 2021). "In SCC tumors, the inhibition of USP28 reduces tumor growth and increases cell death." (PMID 34685632, 2021). "In addition, our study examined the role of USP28 in PC tumorigenesis using cell culture approaches and animal-based tumour models." (PMID 34584067, 2021).
tumor (continued). "The balance between the expression and genetic status of USP28 substrates and regulators could determine the potential role of USP28 as an oncoprotein or tumor suppressor." (PMID 34685632, 2021). "USP28, one of the most studied DUBs, controls key events of tumor progression." (PMID 32560247, 2020). "Therefore, inhibiting the catalytic activity of USP28 is likely to be a suitable mechanism to target ∆Np63 in SCC tumours." (PMID 32128997, 2020). "In a second series of experiments, we assessed a potential role of USP28 in tumour engraftment." (PMID 32128997, 2020). "Taken together, these results indicate that the protease USP28 may regulate distinct oncogenic routes, each of them likely contributing to maintain the tumor phenotype of SCCs." (PMID 32560247, 2020). "To ablate USP28 during tumour initiation, we used CRISPR/Cas9‐mediated gene targeting." (PMID 32128997, 2020). "As a result, USP28 is required for c-MYC-mediated tumor cell proliferation." (PMID 29415985, 2018). "Furthermore, USP28 was strongly correlated with histopathological grade, clinical stage, tumor number, and recurrence rate." (PMID 29415985, 2018). "In clinical tumor samples, USP28 overexpression is correlated with LSD1 upregulation." (PMID 29415985, 2018). "In this model, USP28 may serve as either a tumor promotor or suppressor depending on the status of autocatalytic ubiquitination of FBW7." (PMID 29415985, 2018). "This raises an interesting question regarding the dual functions of USP28: whether it is oncogenic or tumor-suppressive?" (PMID 29415985, 2018). "Accumulating evidence indicated that miR‐4295 may target USP28 in non‐small lung cancer and high expression of USP28 promoted tumour cells proliferation." (PMID 26756701, 2016). "In the 22 NSCLC specimens, there were 17 case with higher USP28 expression in tumour tissues." (PMID 25656529, 2015). "In conclusion, our data indicated that high expression of USP28 in NSCLC promoted tumour cells proliferation, and miR-4295 may target USP28." (PMID 25656529, 2015). "Moreover, there is a significant correlation between USP28 and immune modulatory factors, clinical staging, checkpoint inhibitor responses, MSI (microsatellite instability), TMB (tumor mutational burden), CNV (copy number variation), MMR (mismatch repair) defects, and DNA methylation." (PMID 40607251, 2025). "Moreover, we concentrate on the impacts of USP28 on diverse hallmarks of cancer and discuss whether USP28 can accelerate or inhibit tumor progression." (PMID 36879346, 2023). "Therefore, we hypothesized that USP28 could be a powerful biomarker in predicting tumor immunotherapy effects." (PMID 37450415, 2023). "In addition, the abnormal expression of USP28 was observed and more likely to correlate with clinical prognosis, protein phosphorylation, immune cell infiltration, immune checkpoints, tumor microenvironment, TMB, MSI, methylation, CNV, and MMR of multiple tumors." (PMID 37450415, 2023). "Targeting USP28 protein abundance at an early stage via inhibition of its activity is therefore a feasible strategy for the treatment of early‐stage lung tumours, and the observed synergism with current standard‐of‐care inhibitors holds the potential for improved targeting of established tumours." (PMID 35364627, 2022). "Finally, restoration of FOXM1 expression abolished the anti-tumour effects of USP28-silencing." (PMID 34584067, 2021). "Hence, loss of USP28 or ∆Np63 changes the cellular fate and signature of SCC tumour cells." (PMID 32128997, 2020).